COX7C (cytochrome c oxidase subunit 7C)
Description:
Component of the cytochrome c oxidase, the last enzyme in the mitochondrial electron transport chain which drives oxidative phosphorylation. The respiratory chain contains 3 multisubunit complexes succinate dehydrogenase (complex II, CII), ubiquinol-cytochrome c oxidoreductase (cytochrome b-c1 complex, complex III, CIII) and cytochrome c oxidase (complex IV, CIV), that cooperate to transfer electrons derived from NADH and succinate to molecular oxygen, creating an electrochemical gradient over the inner membrane that drives transmembrane transport and the ATP synthase. Cytochrome c oxidase is the component of the respiratory chain that catalyzes the reduction of oxygen to water. Electrons originating from reduced cytochrome c in the intermembrane space (IMS) are transferred via the dinuclear copper A center (CU(A)) of subunit 2 and heme A of subunit 1 to the active site in subunit 1, a binuclear center (BNC) formed by heme A3 and copper B (CU(B)). The BNC reduces molecular oxygen to 2 water molecules using 4 electrons from cytochrome c in the IMS and 4 protons from the mitochondrial matrix.
Tractability: Small molecule: a structure with a bound ligand is known. Antibody: UniProt predicts a signal peptide or a membrane-spanning region. PROTAC: ubiquitination databases record sites on it; its protein half-life has been measured.
Gene: Protein-coding gene on chromosome 5 (86,617,905 to 86,621,246, forward strand). Ensembl gene ENSG00000127184.
Subcellular location: Mitochondrion inner membrane
Pathways (Reactome):
Metabolism: Complex IV assembly; Respiratory electron transport
Cellular responses to stimuli: Cytoprotection by HMOX1
Gene Ontology:
Molecular function: protein binding
Biological process: cellular respiration; generation of precursor metabolites and energy; mitochondrial electron transport, cytochrome c to oxygen; oxidative phosphorylation
Cellular component: mitochondrial inner membrane; mitochondrial membrane; mitochondrion; respiratory chain complex IV
Genetic constraint (gnomAD): Loss-of-function variants: 0 observed, 2.89 expected, observed/expected ratio (o/e) 0, 90% interval 0 to 1.02. That is too few expected variants to judge how well the gene tolerates losing a copy. Missense variants: 34 observed, 43.39 expected, observed/expected ratio (o/e) 0.78, 90% interval 0.6 to 1.04. Synonymous variants: 13 observed, 15.34 expected, observed/expected ratio (o/e) 0.85, 90% interval 0.55 to 1.35.
Homologues: Orthologues: macaque COX7C (89% identical), pig COX7C (87% identical), guinea pig COX7C (86% identical), mouse Cox7c (86% identical), rat Cox7cl1 (79% identical), tropical clawed frog cox7c (75% identical), zebrafish cox7c (75% identical), Drosophila melanogaster COX7C (48% identical), Caenorhabditis elegans cox-7C (40% identical).
Diseases named in the same sentence as COX7C in open-access papers:
COX7C is named in the same sentence as 29 diseases in open-access papers, as found by Europe PMC text mining. Sharing a sentence is not in itself a finding about the gene and the disease. The quoted sentences say what the papers report.
Alzheimer disease (4 papers, 2018 to 2025). A progressive, neurodegenerative disease characterized by loss of function and death of nerve cells in several areas of the brain leading to loss of cognitive function such as memory and language. "We detected a significant decrease in the expression of complex I and one of three mitochondrial Alzheimer’s disease risk factors, COX7C, in 5xFAD cortex." (PMID 37171075, 2023). "Additionally, in various metabolism-related diseases, elevated COX7C has been identified as a biomarker, and single nucleotide variants in COX7C have been associated with an increased risk of Alzheimer’s disease." (PMID 41459480, 2025). "Recent studies have revealed Cox7c to be a potential biomarker of pathogenesis in Alzheimer's disease." (PMID 36714532, 2023).
chronic kidney disease (3 papers, 2023 to 2024). Impairment of the renal function secondary to chronic kidney damage persisting for three or more months. "For COX7C no direct link to hypertension has been demonstrated so far, though COX7C expression was increased in PBMCs of chronic kidney disease patients, which often display hypertension." (PMID 38410507, 2024). "Studies have demonstrated that the downregulation of Cox7c is characteristic of chronic kidney disease, supporting the notion that Cox7c is involved in the regulation of mitochondrial function and oxidative stress." (PMID 36909178, 2023). "In addition, studies have shown that COX7C is a key regulator in the physiological processes of numerous diseases, where upregulation of this gene is associated with the development of many cancer tumors and its downregulation is a feature of many chronic kidney diseases." (PMID 36814903, 2023).
Parkinson disease (3 papers, 2018 to 2022). A progressive degenerative disorder of the central nervous system characterized by loss of dopamine producing neurons in the substantia nigra and the presence of Lewy bodies in the substantia nigra and locus coeruleus. "This analysis revealed that the genes implicated in Parkinson’s disease (Atp5a1, Ndufa7, Ndufb2, Ndufs8, Park7, Cox7a2, Cox7c, Cox6b1, Cycs, Uchl1) were upregulated in thia-exposed mice (p-value = 4.2E-3)." (PMID 34295895, 2021).
Sepsis (3 papers, 2022 to 2024). Sepsis is defined as life-threatening organ dysfunction caused by a dysregulated host response to infection. "First, COX7C is a protein-coding gene that has only been shown to be related to pathways, including complex mitochondrial assembly and ATP synthesis, plays an essential role in cellular energy metabolism, and is a potential biomarker for diabetes-related sepsis (DRS)." (PMID 39452046, 2024). "Similar to these studies, our investigation of co-expressed genes, aimed at gaining a better understanding of the relationship between diabetes and sepsis, revealed UBE2D1 and COX7C as potential biomarkers and therapeutic targets for DRS." (PMID 35445133, 2022).
bladder cancer (2 papers, 2016 to 2023). "Other studies have reported that upregulation of Cox7c is associated with the occurrence of some tumors, such as skin cancer, breast cancer, and bladder cancer." (PMID 36909178, 2023). "In a subset analysis of whole blood samples obtained before cancer diagnosis, we identified a signal in the promoter of COX7C, at the same site where whole blood DNA methylation was previously associated with bladder cancer." (PMID 26798410, 2016).
breast carcinoma (2 papers, 2023 to 2025). "Notably, NDUFA4 is associated with immune modulation, PD-L1 expression, and breast cancer prognosis, while altered expression of COX6C and COX7C, subunits of cytochrome c oxidase, is linked to poor cancer prognosis." (PMID 40618351, 2025).
colon cancer (2 papers, 2023 to 2025). "Upregulation of COX7C has been observed in colon cancer and skin squamous cell carcinoma, where it is implicated in disease development and response to chemotherapy." (PMID 41459480, 2025). "A recent study found that the expression of Cox7c was correlated with venous thromboembolism in patients with colon cancer." (PMID 36909178, 2023).
COVID-19 (2 papers, 2022 to 2023). A disease caused by infection with severe acute respiratory syndrome coronavirus 2. "In the COVID-19 group, coagulation factor XIII A chain (F13A1) and contactin associated protein 2 (CNTNAP2) exhibited the strongest upregulation, with CD14, C1QC, cytochrome C oxidase subunit 7C (COX7C) and (APOE) being increased in the AD group." (PMID 36211330, 2022).
diabetes (2 papers, 2022 to 2023). "COX7C (cytochrome C oxidase subunit 7C) is an enzyme in the electron transport chain related to cellular respiration and is also a potential biomarker of diabetes mellitus." (PMID 37293508, 2023).
Huntington disease (2 papers, 2018 to 2021). Huntington disease (HD) is a rare neurodegenerative disorder of the central nervous system characterized by unwanted choreatic movements, behavioral and psychiatric disturbances and dementia. "Interestingly, several mitochondrial proteins involved in AD, PD and Huntington's disease were only significantly changed in the chronic low dose group, such as ATP synthase subunit epsilon (P56382), Cytochrome c oxidase subunit 7C (P17665), Cytochrome c oxidase subunit 6A1 (P43024)." (PMID 34197336, 2021).
amyloidosis (1 paper, 2021). A disorder characterized by the localized or diffuse accumulation of amyloid protein in various anatomic sites. "The MMSE‐correlated DEPs were mainly involved in amyloidosis (DNM1, UBR1, OPTN, FERMT2), CNS disorder (WIPF1) and energy metabolism (COA6, COX7C, PDPR) processes." (PMID 34528736, 2021).
Arthritis (1 paper, 2025). Inflammation of a joint. "COX7C demonstrated significant upregulation in most arthritis samples compared to HCs (p < 0.05)." (PMID 41459480, 2025).
Cerebral ischemia (1 paper, 2023). Restriction of arterial blood supply to the brain associated with insufficient oxygenation to support the metabolic requirements of the tissue. "Our study demonstrated the inhibition of the mitochondrial apoptosis pathway and the upregulation of the HIF-1α/VEGF pathway by Cox7c, resulting in a neuroprotective effect during cerebral ischemia/reperfusion." (PMID 36909178, 2023). "In conclusion, our study proposed for the first time the possible beneficial effects of Cox7c as a key target of NBP in the processes of cerebral ischemia and injury repair." (PMID 36909178, 2023). "In contrast, the expression of Cox7c was significantly decreased in vascular endothelial cells subjected to cerebral ischemia, and the expression of Cox7c was upregulated by NBP treatment." (PMID 36909178, 2023). "At present, studies regarding the role of Cox7c in cerebral ischemia/reperfusion are still rare." (PMID 36909178, 2023). "However, rare research reported the role of Cox7c in cerebral ischemia/reperfusion currently, therefore we conducted a series of studies focusing on Cox7c." (PMID 36909178, 2023).
Cognitive impairment (1 paper, 2020). Abnormal cognition is characterized by deficits in thinking, reasoning, or remembering. "In our results, COX7C was collected as hub genes which may suggest that mitochondrial dysfunction in patients with cognitive impairment is a sign of disease aggravation." (PMID 33204697, 2020).
Stroke (1 paper, 2024). Sudden impairment of blood flow to a part of the brain due to occlusion or rupture of an artery to the brain. "Core genes (UQCRQ, USMG5 [ATP5MD], COX6C, NDUFB3, ATP5L [ATP5MG], COX7C, NDUFA1, NDUFA4) were highly expressed in septic shock and stroke samples." (PMID 39655053, 2024).
type 2 diabetes (1 paper, 2024). "We found potential genetic biomarkers for MCI in patients with type 2 diabetes using WGCNA combined with the LASSO algorithm and further screened four genes, COX7C, SNRPG, TOMM7, and RPS24, which are associated with the occurrence of type 2 diabetes." (PMID 39452046, 2024). "In addition, we verified that four of these genes (COX7C, SNRPG, TOMM7, and RPS24) are also able to predict the risk of type 2 diabetes and can be used as key genes in type 2 diabetes and MCI." (PMID 39452046, 2024). "The t-test results showed that the expression levels of four genes (COX7C, SNRPG, TOMM7, and RPS24) were significantly different between the type 2 diabetes and control groups (p < 0.05)." (PMID 39452046, 2024). "The ROC curve was screened by integrating the GEO database, and revealed COX7C, SNRPG, TOMM7, and RPS24 as key genes in the progression of type 2 diabetes." (PMID 39452046, 2024).
cancer (4 papers, 2016 to 2025). A tumor composed of atypical neoplastic, often pleomorphic cells that invade other tissues. "EWAS in the 15 MZ pairs was performed using the same approach as the analyses in the 41 MZ twin pairs, and the top-ranked results included signals in the promoters (within 200 bp of the TSS) of genes COX7C and U2AF1 that have been previously linked to cancer." (PMID 26798410, 2016). "We next explored the relationship between the time of blood sample extraction and the observed DNA methylation differences in cancer-discordant twins at the four top-ranked pan-cancer DMPs and the pan-cancer DMP located at COX7C identified above in more depth." (PMID 26798410, 2016).
COX7C also shares sentences with these, for which no sentence is quoted: tumor (2 papers); autoimmune uveitis (1); dyslipidemia (1); Hypertension (1); influenza infection (1); liver cancer (1); non-alcoholic fatty liver disease (1); skin cancer (1); skin squamous cell carcinoma (1); type 1 diabetes (1); uveitis (1); venous thromboembolism (1).